CEMIP (cell migration inducing hyaluronidase 1)
Diseases named in the same sentence as CEMIP in open-access papers (continued):
Sharing a sentence is not in itself a finding about the gene and the disease.
cancer (continued). "A previous study showed that hypoxia induces CEMIP expression in cancer cells via direct binding of HIF-2α to a hypoxia response element in the CEMIP promoter." (PMID 31303964, 2019). "Our findings suggest that overexpression of CEMIP confers an adaptive advantage to cancer cells, which facilitates cell survival and tumor growth." (PMID 31303964, 2019). "Other reports have shown that CEMIP can suppress apoptosis via epidermal growth factor receptor (EGFR) signaling as well as by enhancing glycogen breakdown to promote cancer cell survival." (PMID 31303964, 2019). "In 2 patients whose CEMIP and CA 19-9 levels were serially checked two times with tumor response evaluation, CEMIP showed a predictive function for treatment response, and it accurately predicted cancer progression compared to CA 19-9." (PMID 29467409, 2018). "This inverse correlation between upregulated CEMIP and downregulated E-cadherin in cancer cells at the invasive front reinforces the role of CEMIP in cancer EMT." (PMID 26009875, 2015). "Together, these studies demonstrate the vital role of CEMIP in cancer progression and warrant further investigation into the regulatory mechanism(s) of CEMIP expression in cancer." (PMID 26009875, 2015). "Together, our data reveals a regulatory cascade through which hypoxic stress leads to upregulated CEMIP in cancer cells." (PMID 26009875, 2015). "All 29 cancers showed a greater than 12-fold increase in CEMIP expression over matched normal colon mucosa, with a median increase of 54-fold." (PMID 26437221, 2015). "The present study has unraveled a novel cascade of the regulatory mechanism of CEMIP in human cancer progression." (PMID 26009875, 2015). "In contrast, several other recent reports including the observation presented here support CEMIP's role in enhancing cancer cell migration, hence contributing to increased cancer cell invasion through different signaling pathways." (PMID 26009875, 2015). "Together, these data suggest a cascade of hypoxia-HIF-2α-CEMIP upregulation in enhancing cell migration as an escape mechanism for cancer cells to migrate away from hypoxic areas." (PMID 26009875, 2015). "Our data support CEMIP as a novel cancer invasion-promoting gene that is induced upon exposure of cancer cells to hypoxic conditions as part of the reprogramming associated with increased migratory capacity." (PMID 26009875, 2015). "Together, these results suggests that under normoxic conditions, the H3K4me3 activation mark is maintained at a low level within the CEMIP promoter region in less aggressive cancer cell lines, therefore leading to lower expression levels of CEMIP." (PMID 26009875, 2015). "The key mechanistic finding in our study is that hypoxia promotes CEMIP expression in invasive cancer cells." (PMID 26009875, 2015). "With recent reports highlighting the functional significance of CEMIP in cancer cell survival, migration and invasion, the need to ascertain the mechanism of upregulation of CEMIP in cancer cells is imperative." (PMID 26009875, 2015). "Our findings are supported by studies in other cancers demonstrating CEMIP can protect cervical, gastric, and breast cancer cells from apoptosis, though the exact molecular mechanism of CEMIP's anti-apoptotic effect has yet to be elucidated." (PMID 26437221, 2015). "Overall, characterizing the effect of Jarid1A on CEMIP is the first step towards gaining a better understanding of the epigenetic regulatory mechanisms governing the expression of CEMIP in cancer." (PMID 26009875, 2015). "Discovering the mechanism by which cancer cells specifically induce CEMIP, leading to a more aggressive phenotype, can have a positive impact on potential therapies targeting this gene." (PMID 26009875, 2015). "To determine the role of Jarid1A in the regulation of CEMIP expression, we first surveyed cancer cell lines for expression of Jarid1A and CEMIP." (PMID 26009875, 2015).
cancer (continued). "In contrast, strong positive staining of CEMIP was found in cancer cells located at the invasive front or cells invading into the submucosa layer." (PMID 26009875, 2015). "Western blotting analysis revealed an inverse correlation between Jarid1A and CEMIP in cancer cell lines." (PMID 26009875, 2015). "Recently, KIAA1199 was discovered to be a cell-migration inducing protein (renamed CEMIP) that is upregulated in human cancers." (PMID 26009875, 2015). "Furthermore, microRNAs wield post-transcriptional regulation over CEMIP expression, highlighting the intricate control mechanisms underpinning its oncogenic role across various cancers." (PMID 38390387, 2024). "CEMIP expression is correlated with increased tumor metastases and poor prognosis in numerous cancers, suggesting that CEMIP hyaluronidase activity may be contributing to the ability of tumor cells to migrate and colonize other tissues." (PMID 39454959, 2024). "In addition to its involvement in cancer, CEMIP interacts with various signaling molecules such as transcription factors, EGFR, and the Wnt/β-catenin pathway, participating in essential cellular activities." (PMID 38390387, 2024). "While identified as a biomarker for several diseases, CEMIP’s mechanism in cancer seems distinct." (PMID 38390387, 2024). "Expanding investigations across various cancer types might unveil distinct tissue-specific regulators governing CEMIP transcriptional control." (PMID 38390387, 2024). "Elevated CEMIP expression correlates with poor prognosis across various cancers." (PMID 38390387, 2024). "Additionally, in LNCaP and PC-3 PCa cells, CEMIP inhibits ferroptosis, thereby facilitating cancer cell migration." (PMID 37576552, 2023). "Overall, this study found that CEMIP expression is higher in cancer tissues than in noncancerous tissues and that high CEMIP expression is associated with distant metastasis and death." (PMID 35370456, 2022). "High levels of CEMIP are also secreted from other types of cancer." (PMID 36291875, 2022). "Although not always explicitly investigated, the roles that these pathways are known to play in the process of tumorigenesis and metastasis suggest that CEMIP may contribute to the growth, dissemination, and spread of cancer through regulating these pathways." (PMID 36291875, 2022). "Conversely, chronic inflammatory microenvironments stimulate EMT in the context of cancer; thus, if CEMIP expression contributes to creating such microenvironments, this may be another means through which it promotes EMT." (PMID 36291875, 2022). "CEMIP mRNA levels were higher in cancer tissues than in normal tissues." (PMID 35370456, 2022). "However, another study indicated that CEMIP has antitumor characteristics, leading to a more complex role in cancer regulation." (PMID 36451490, 2022). "CEMIP plays a role in the pathogenesis of several diseases, including cancer." (PMID 36291875, 2022). "Herein, we summarize the process in recent studies of CEMIP, especially in cancer research." (PMID 36451490, 2022). "However, minimal studies are available regarding the context-specific functionality of CEMIP in cancer cell survival in suspension conditions." (PMID 35013120, 2022). "Compared with normal tissue, CEMIP expression is strongly upregulated in many types of cancer." (PMID 36291875, 2022). "Additionally, we explored CEMIP expression based on TCGA research network, which also displayed higher (9.094-fold) levels of CEMIP in cancer compared to normal breast tissues." (PMID 35370456, 2022). "Can specific microRNAs serve as therapeutic tools for CEMIP-related diseases such as cancer?" (PMID 36451490, 2022). "CEMIP acts as an oncogene, regulating multiple signal pathways in a variety of malignant tumors, however, it remains unknown whether Notch signaling pathway has been involved in CEMIP-regulated carcinogenesis of tumors." (PMID 35957875, 2022).
cancer (continued). "Furthermore, research has indicated that CEMIP is aberrantly expressed in multiple types of cancers, such as colorectal, gastric, breast, pancreatic, cervical, and liver cancer." (PMID 35655258, 2022). "The role of CEMIP in epithelial-to-mesenchymal transition of cancer cells is already well known." (PMID 35474501, 2022). "Therefore, we performed an integrated analysis of CEMIP in BC and other cancers using bioinformatics approaches and a variety of online analysis tools mainly based on TCGA and GEO databases." (PMID 34966410, 2021). "Subsequently, we conducted a pan-cancer analysis of CEMIP expression based on the TCGA database and discovered that it was highly expressed in most cancers, consistent with early studies, after which we focused on CEMIP expression in BC." (PMID 34966410, 2021). "In addition to being upregulated in STAD, CEMIP expression was also upregulated in a variety of cancers, including lung adenocarcinoma, colon adenocarcinoma, and head and neck squamous cell carcinoma." (PMID 34338150, 2021). "3.CEMIP down-regulation inhibits the biological behavior of cancer cells." (PMID 34338150, 2021). "Other research studies revealed that CEMIP residing in the endoplasmic reticulum may enhance BC cell survival in hypoxia and cancer cell migration by upregulating and interacting with binding immunoglobulin protein." (PMID 34966410, 2021). "David Lyden and coworkers demonstrated that exosomal CEMIP protein could be delivered to distant recipient cells (brain endothelial and microglial cells) to promote vascular remodeling and cancer metastasis." (PMID 32754443, 2020). "Interestingly, an investigation has revealed that CEMIP can be enclosed in exosomes involved in cancer metastasis." (PMID 32754443, 2020). "Moreover, CEMIP overexpression confers protective adaptations to cancer cells under hypoxic conditions, by decreasing apoptosis, activating autophagy, and increasing glucose uptake, to facilitate tumor growth." (PMID 31303964, 2019). "Identifying the correlation between CEMIP and BiP expression as well as the protective functions that they provide to cancer cells exposed to hypoxia could lead to the development of more efficient chemotherapeutics." (PMID 31303964, 2019). "However, CEMIP has been reported to play roles in cancer cell proliferation and invasion either negatively or positively and its role in the tumor progression of HGNET-BCOR remains to be clarified." (PMID 29371980, 2017). "It would be interesting to examine the methylation patterns of cancer cells versus normal tissue to determine if there is a complete lack of methylation within the CEMIP promoter in noncancerous tissue, which would further explain the upregulation of CEMIP." (PMID 26009875, 2015). "Moreover, requirement of upregulated CEMIP in HIF-2α-mediated cell migration further highlights the importance of CEMIP in cancer dissemination." (PMID 26009875, 2015). "Based on CEMIP's role in cancer cell invasiveness, we hypothesized that exposure to hypoxic conditions could lead to the upregulation of CEMIP in cancer cells resulting in cancer dissemination." (PMID 26009875, 2015). "Since CEMIP mRNA level has been reported to be upregulated in human cancer specimens using samples from bulk tumor tissues and TMA samples have limited representation of primary tumors, we next examined formalin-fixed, paraffin-embedded (FFPE) individual human colon specimens using IHC." (PMID 26009875, 2015). "However, CEMIP has been reported to play roles in cancer cell proliferation and invasion either negatively or positively." (PMID 26009875, 2015). "Given the consideration that proteolytic activity and cell migratory ability are two key requirements for cancer invasion, Tiwari's observation suggests CEMIP may reduce proteolytic activity of cancer cells, therefore inhibiting cell invasion." (PMID 26009875, 2015).
cancer (continued). "Additionally, CEMIP is involved in the regulation of multiple signal pathways, including EMT, MEK/ERK, AMPK, Wnt/β-catenin, Ras/Raf/Erk and PI3K/AKT, all of which are linked to the development of malignant tumors." (PMID 35957875, 2022). "Furthermore, CEMIP is vital for the proliferation, migration, and invasion of cancer cells." (PMID 35013120, 2022). "TIMER2.0 was employed to investigate the mRNA expression level of CEMIP across a variety of cancers based on the TCGA dataset, which was expressed higher in 13 kinds of cancers other than normal controls (p < 0.05), including BC, but lower in other three types of cancer." (PMID 34966410, 2021). "Accumulated evidence shows that the over-expression of CEMIP could enhance proliferation, adhesion, motility, invasiveness, and EMT of various carcinomas, including BC, as well as its transcriptional regulation mechanism in many cancers, indicating that CEMIP might play an important role in BC." (PMID 34966410, 2021). "We illustrated that CEMIP was highly expressed in various kinds of carcinomas, including BC, especially advanced subtypes, and predicted less favorable prognosis (negatively associated with overall survival) in BC patients, which might be an independent prognostic factor." (PMID 34966410, 2021). "In addition to the top 10 most vital proteins, we also surprisingly found other important proteins among the DEPs, such as CEMIP (cell migration-inducing and hyaluronan-binding protein), which could play an important part in cancer metastasis." (PMID 32754443, 2020). "A better understanding of these processes might elucidate the basic biology of how specific responses to hypoxia are coordinated, and how pharmacological manipulation of hypoxia-related pathways might be developed to interfere with CEMIP expression in human cancer." (PMID 26009875, 2015). "Increased levels of LMWHA in malignant tumors suggest that HAS3, CEMIP, and CEMIP2 function as key enzymes." (PMID 39858106, 2025). "It is particularly important to understand the two pathways of HA degradation in malignant tumors, one involving HAYL1/HYAL2 and the other CEMIP/CEMIP2." (PMID 39858106, 2025). "Targeting CEMIP hyaluronidase activity with therapeutic small molecule inhibitors may therefore be an efficacious method to promote repair following CNS insults, reduce cancer cell metastasis to the brain, and reverse other pathological conditions linked to elevated HA catabolism." (PMID 39454959, 2024). "Many of the genes upregulated, i.e., MMP1, MMP13, S100A7, CEMIP, and CA9 are known to increase in various cancer cells." (PMID 36766731, 2023). "The TF-protein NFKB1 (a regulator of GUCA2A, CA4, CEMIP and MS4A12) is a suppressor of inflammation, ageing and cancer." (PMID 36991484, 2023). "The expression of TF-protein YY1 (a regulator of CXCL8, ADH1C, CEMIP, ZG16, and CLCA4) contributes to tumor growth differs in different cancers." (PMID 36991484, 2023). "The cancer cell lines mainly expressed TMEM2 hyaluronidase, whereas the non-transformed cells predominantly expressed its paralog KIAA1199/CEMIP, while TMEM2 was expressed to a lesser extent." (PMID 36497283, 2022). "The cell migration-inducing protein (CEMIP), also called KIAA1199, had increased expression in cancers and functioned as a regulator related to cell survival, growth, and invasion." (PMID 34039961, 2021). "For example, upregulation of CEMIP, RRM2, LAMC2, SCD, TNS4, and PLAU in humans is prognostically unfavorable for various cancers; these genes have CR-upregulated mouse orthologs." (PMID 34202278, 2021). "Cell migration-inducing and hyaluronan-binding protein (CEMIP) is a Wnt-related protein involved in memory and synapse formation, as well as in cancer and inflammatory processes." (PMID 34338150, 2021). "Some studies reported that CEMIP is involved in EMT, Wnt/β-catenin, MEK/ERK, and PI3K/Akt signal pathways to promote cancer progression, while the exact mechanism is still ambiguous." (PMID 34966410, 2021).
cancer (continued). "The results showed that CST1, CEMIP, COL8A1, PMEPA1, and MSLN were upregulated in most cancers and were downregulated in a few." (PMID 34338150, 2021). "Previous studies suggests that KIAA1199 (also termed as CEMIP) is overexpressed, prognostic, and correlated with the malignant behavior in a variety of cancers." (PMID 28179576, 2017). "However, the mechanism of induction of CEMIP in cancer was hitherto unknown." (PMID 26009875, 2015). "Evidence showed that overexpressed CASC19 elevated the expressions of CEMIP and EMT biomarkers in CRC cells, which can be reversed by inducing the expression of miR-140-5p in cells; they were highly correlated with the poor cancer prognosis." (PMID 40746360, 2025). "Additionally, the diverse molecular functions of CEMIP across various cellular pathways could contribute to these conflicting observations, highlighting the need for further comprehensive investigations to elucidate its precise role in different cancer contexts." (PMID 38390387, 2024). "It is possible, therefore, that CEMIP activity only contributes to cancer cell metastasis but not tumor growth, although studies of the effects of blocking CEMIP activity in vivo are needed to confirm these findings." (PMID 39454959, 2024). "The biological role of CEMIP has been studied in cancer biology in humans, but it has not been described in other species including the dog." (PMID 36012418, 2022). "Hypoxia stimulates CEMIP-dependent motility in colorectal and PDAC cancer cells." (PMID 36291875, 2022). "Western blotting and database analysis showed that CEMIP was significantly highly expressed in carcinomas compared to nontumor tissues." (PMID 35370456, 2022). "Some studies have shown that KIAA1199 (CEMIP) is a transmembrane protein expressed in many types of noncancerous cells and cancer cells." (PMID 33197891, 2020). "Since CEMIP is regulated by HIF-2α, targeting HIF-2α may inhibit cancer cell migration hence blocking cancer cell invasion." (PMID 26009875, 2015). "Analysis of the various cancers revealed that several putative REST target genes, including Polo Like Kinase 1 (PLK1), ADAM Metallopeptidase Domain 12 (ADAM12), Troponin T1 (TNNT1), and cell migration-inducing and hyaluronan-binding protein (CEMIP, KIAA1199) were highly dysregulated." (PMID 35177031, 2022). "Additionally, case 2 also exhibited a CEMIP-MTHFS fusion in both the primary tumor and metastasis, a fusion that has not been previously associated with cancer." (PMID 33827048, 2021). "On the other hand, accumulated cell- and animal-based evidence shows that the over-expression of CEMIP could enhance proliferation, survival, adhesion, motility, invasiveness, and epithelial-to-mesenchymal transition (EMT) of various cancer cells." (PMID 34966410, 2021). "In addition, cell migration-inducing and hyaluronan-binding (CEMIP) protein in tumor exosomes from brain metastasis, but not from lung or bone metastatic cells, may promote cancer cell colonization." (PMID 33821195, 2021).